STAT4 (signal transducer and activator of transcription 4)
Diseases named in the same sentence as STAT4 in open-access papers (continued):
Sharing a sentence is not in itself a finding about the gene and the disease.
depression (7 papers, 2012 to 2025). "According to the validated datasets, Stat4 and Col1a2 were particularly strongly associated with the comorbidity of heart failure and depression." (PMID 39295096, 2024). "Heart failure comorbid with depression may be associated with five hub genes, including Stat4, Cd83, Cx3cr1, Col1a2, and Sh2d1b." (PMID 39295096, 2024). "The results show that a total of 5 pivotal genes, CD83, CX3CR1, STAT4, COL1A2, and SH2D1B, of which STAT4 and COL1A2 are important underlying the co-morbidity mechanism of heart failure and depression." (PMID 38084332, 2023). "STAT4 has been proposed as a potential biomarker for HF comorbid with depression." (PMID 40873619, 2025). "The mRNA expression profile associated with Any Depression (AD) included four genes, three of them (PDGFA, PF4, and TGF-β1) were down-regulated (P-values: <0.0054, <0.0123 and <0.0152; respectively), while the STAT4 gene was up-regulated (P-value <0.0396)." (PMID 23139898, 2012). "Of note, in our study, we observed a significant baseline up-regulation of STAT4 in HCV patients with both a history of depression and new treatment-related depression." (PMID 23139898, 2012).
juvenile idiopathic arthritis (7 papers, 2014 to 2023). Juvenile idiopathic arthritis (JIA) is the term used to describe a group of inflammatory articular disorders of unknown cause that begin before the age of 16 and last over 6 weeks. "Another study demonstrated a statistically significant contribution of STAT4 to juvenile idiopathic arthritis." (PMID 29881250, 2018).
Stroke (7 papers, 2011 to 2025). Sudden impairment of blood flow to a part of the brain due to occlusion or rupture of an artery to the brain. "There is evidence suggesting that the HLA-DRB1*04/*13 genotype and the single nucleotide polymorphism (SNP) rs10181656 in STAT4, which encodes the signal transducer and activator of transcription 4, are linked to strokes in individuals with SLE." (PMID 40151747, 2025). "Interestingly, the STAT4 risk allele has been shown to be a risk factor for stroke and anti-phospholipid antibodies in patients with SLE." (PMID 24386384, 2013). "The HLA-DRB1Ã04 genotype and STAT4 rs10181656 were associated with stroke in SLE independent of the status of APL." (PMID 35964089, 2022). "The expression level of p-STAT4 signal increased in CD4 T cells, CD4 Tem cells, CD8 Tem cells, B cells, Tregs, NK cells, cDCs and monocytes was dramatically increased after stroke." (PMID 34094644, 2021).
autoimmune thyroid disease (6 papers, 2014 to 2023). Inflammatory disease of the thyroid gland due to autoimmune responses leading to lymphocytic infiltration of the gland. "Ni Yan and coauthors investigated the association of STAT4 polymorphisms with autoimmune thyroid diseases." (PMID 38275379, 2023). "The association between STAT4 rs7574865 polymorphism and the susceptibility of autoimmune thyroid disease (AITD) has been investigated in previous case-control studies." (PMID 30666271, 2018). "Analysis of genotype and allele distribution of three STAT4 SNPs in AITD (autoimmune thyroid disease) patients and controls." (PMID 25019342, 2014). "The study, published in 2014, concluded that the STAT4 rs7574685 T allele and the STAT4 rs10181656 G allele were statistically significantly associated with the occurrence of thyroid autoimmune diseases such as Graves and Hashimototis in the Chinese Han population." (PMID 38275379, 2023). "Some studies found that the STAT4 rs7574865 polymorphism increases autoimmune thyroid diseases in the general population but not in psoriatic patients." (PMID 33585138, 2021).
endometriosis (6 papers, 2020 to 2025). The growth of functional endometrial tissue in anatomic sites outside the uterine body. "Both STAT4 rs7574865 and rs7582694 SNPs have been associated with an increased risk of both endometriosis and SLE." (PMID 40725086, 2025). "The TT genotype of STAT4 rs7574865 G/T polymorphism was found to be more frequent in women with minimal or mild endometriosis compared to the controls." (PMID 40725086, 2025). "Endometriosis, ovarian cancer (OC), and chronic lymphocytic leukemia (CLL) B cells have also been found to be associated with STAT4 in recent years." (PMID 32226303, 2020). "miR-20a via ERG/HLX/STAT4/perforin axis could mediate the cytotoxicity of natural killer (NK) cells in endometriosis." (PMID 32850438, 2020). "Our results show that several mRNAs and pathways related to immune function, such as IL-1B, CXCR4, IL-7R, STAT4, CD14, and CCR5, as well as the FoxO signaling pathway, the Jak-STAT signaling pathway, and the NF-kappa B signaling pathway, have significant correlations with endometriosis." (PMID 38203209, 2023).
glioma (6 papers, 2019 to 2025). A benign or malignant brain and spinal cord tumor that arises from glial cells (astrocytes, oligodendrocytes, ependymal cells). "Therefore, within the context of intratumoral bacteria-associated glioma, STAT4 emerges as an indispensable molecule in tumor-associated immune regulation." (PMID 39660865, 2025). "We confirmed that the expression profiles of relevant IL-12R genes (Il12rb1, Il12rb2, and Stat4) are comparable between human gliomas and the murine GB cell lines (CT-2A, GL261, and 005), supporting the utility of these mouse models for studying IL-12-mediated mechanisms in GB." (PMID 40842154, 2025). "Studies investigating the expression and function of the STAT4 gene in glioma are rare." (PMID 34276757, 2021). "However, the expression level of STAT4 mRNA was lower in glioma than in normal controls." (PMID 34276757, 2021). "No apparent correlations between the mRNA expression of STAT4 and the prognosis of glioma were found in either the TCGA or CGGA datasets." (PMID 34276757, 2021). "No apparent correlation between STAT4 expression and the prognosis of glioma was observed." (PMID 34276757, 2021). "Western blot analyses demonstrated that, whereas STAT2 and STAT4 showed no prominent or consistent changes in expression, STAT1, STAT3 and STAT5 expression were increased in glioma tissues compared with neighboring non-tumor tissue." (PMID 31530290, 2019).
heart failure (6 papers, 2012 to 2024). Inability of the heart to pump blood at an adequate rate to meet tissue metabolic requirements. "Moreover, large numbers of TNF-α-producing cells and high levels of STAT4 mRNA were associated with the occurrence of heart failure." (PMID 22811738, 2012). "At any event, STAT4 mRNA was overexpressed in CCC patients with heart failure as compared with STAT6 levels in patients with presence or absence of heart failure, a further indication of TH1 signaling." (PMID 25152568, 2014). "The local production of IFN-γ is functional, since STAT4 mRNA was overexpressed in subjects with heart failure." (PMID 22811738, 2012). "Moreover, STAT4 levels were significantly higher than STAT6 levels in the heart failure group." (PMID 22811738, 2012). "Furthermore, LDA analysis revealed significantly higher STAT4 levels in patients with heart failure compared to those without heart failure." (PMID 22811738, 2012).
liver cancer (6 papers, 2011 to 2023). An epithelial or non-epithelial malignant neoplasm that arises from the liver. "In the past ten years, scientists have proved that STAT4 single nucleotide polymorphism is closely related to the occurrence of liver cancer." (PMID 34675977, 2021). "Through the detection of collected liver cancer tissues and cell lines, it is found that high STAT4 expression is associated with a poor prognosis, indicating that STAT4 plays an important role in promoting the generation and development of liver cancer and may be a potential oncogene." (PMID 34675977, 2021). "Conversely, STAT4 protein was expressed at lower levels in liver cancer tissues than normal tissues." (PMID 38107057, 2023). "As far as is known, this is the first study on miR-141 targeting the new gene STAT4 to regulate the proliferation and metastasis of liver cancer cells, and it has a certain application value." (PMID 34675977, 2021). "The main finding of this study is that miR-141 inhibits the proliferation and metastasis of liver cancer cells by targeting the expression of the STAT4 gene." (PMID 34675977, 2021). "qRT-PCR was used to test the expressions of miR-141 and STAT4 in collected liver cancer tissues and adjacent tissues, cultured liver cancer cell lines MHCC97H, Hep3B, and Huh7, and normal human liver cells HL7702." (PMID 34675977, 2021). "At the cellular level, miR-141 reduces the expression of the proteins that promote the metastasis and proliferation of liver cancer by targeting STAT4 and coordinately regulates the proliferation, migration, and invasion of liver cancer cells." (PMID 34675977, 2021). "First, qRT-PCR was used to detect the expression levels of miR-141 and STAT4 in the cancer tissues and normal liver tissues of the 121 liver cancer patients." (PMID 34675977, 2021). "In this study, the Transwell experiment was used to analyze the effect of low STAT4 expression on the invasion and migration of liver cancer cells." (PMID 34675977, 2021). "miR-141 can target the STAT4 gene expression to inhibit the proliferation, migration, and invasion of liver cancer cells." (PMID 34675977, 2021). "This study proved through experiments and data that miR-141 can inhibit the proliferation and metastasis of liver cancer cells by targeting the gene STAT4, which provides some theoretical reference for the mechanism of miR-141 regulating STAT4 in liver cancer cells." (PMID 34675977, 2021). "According to the previous test results, STAT4 is highly expressed in liver cancer tissues." (PMID 34675977, 2021). "Seven TFs (FOXA1, FOXA2, RARG, STAT4, MEF2C, SOX18, and GXS2) have been identified to be likely to affect the metabolism, development, differentiation and proliferation of liver cancer in previous studies." (PMID 29033978, 2017). "Additionally, six of the 25 significant liver cancer pathways are immune– and inflammation–related, namely, antigen processing and presentation (two, with 60% overlap), classical complement pathway, corticosteroids, IL12 signaling mediated by STAT4, and NO2-dependent IL-12 pathway in NK cells." (PMID 21695280, 2011).
lymphoma (6 papers, 2014 to 2026). A malignant (clonal) proliferation of B- lymphocytes or T- lymphocytes which involves the lymph nodes, bone marrow and/or extranodal sites. "Studies have also shown that chemotherapy-induced STAT4 deficiency can help lymphoma patients transplanted with peripheral blood stem cells to produce IFN-γ, thereby inhibiting the growth of tumor cells." (PMID 34100914, 2021). "We have previously reported that post-transplant lymphoma patients have an acquired deficiency of signal transducer and activator of transcription 4, which results in defective IFNγ production during clinical immunotherapy." (PMID 24363024, 2014). "STAT4 deficiency was observed in lymphoma patients after PBSCT." (PMID 24363024, 2014). "Thus, incorporating lunasin into cytokine-based treatment may rescue the production of IFNγ by NK cells from heavily treated lymphoma patients with acquired STAT4 deficiency." (PMID 24363024, 2014). "Together, EATL appears driven by STAT3-mediated inflammation and immune evasion, while MEITL is a cytotoxic lymphoma with high expression of innate-like T/NK-cell genes (e.g., STAT4, NCAM1) and an “immune-cold” profile with low inflammation." (PMID 41057685, 2026). "Then, we compared STAT4 protein expression between low and high miR-141/200c-expressing T-cell leukemia/lymphoma lines." (PMID 37173993, 2023). "Consistent with previous studies, for example, IL-2 can regulate STAT4 to enhance the function of natural killer cells, and it can lead to the down-regulation of STAT4 protein during the treatment of lymphoma, which results in STAT4 defects and affects the therapeutic effect." (PMID 41010015, 2025). "STAT4 and STAT6 genes are inversely regulated in CTCL and the loss of expression of the former may play a role in switching to Th-2 answer in the advanced lymphoma stages." (PMID 34948183, 2021).
pancreatic cancer (6 papers, 2015 to 2025). "EdU proliferation and colony formation assays revealed that TCN1 knockdown significantly suppressed pancreatic cancer cell proliferation, whereas STAT4 overexpression rescued this inhibitory effect." (PMID 41154358, 2025). "To further delineate the mechanism through which the TCN1/STAT4/DUOX2 axis promotes pancreatic cancer malignancy, we systematically performed functional rescue experiments in BxPC-3 and PANC-1 cells." (PMID 41154358, 2025). "STAT4 protein expression was significantly higher in pancreatic cancer than in non‐cancerous pancreatic tissue, and may serve as a biomarker for pancreatic cancer development and deterioration." (PMID 38107057, 2023). "In addition, STAT4 has been reported to promote angiogenesis in pancreatic cancer by inducing IL8 transcription." (PMID 35224833, 2022). "However, the exact role of STAT4 in pancreatic cancer remains unclear." (PMID 35433680, 2022).
Renal insufficiency (6 papers, 2013 to 2025). A reduction in the level of performance of the kidneys in areas of function comprising the concentration of urine, removal of wastes, the maintenance of electrolyte balance, homeostasis of blood pressure, and calcium metabolism. "In our previous study, the STAT4 SNP rs7582694 was associated with LN with severe renal insufficiency (glomerular filtration rate <30 mL/min/1.73m2)." (PMID 34127828, 2021). "Despite the low number of cases, LN patients who had developed severe renal insufficiency (n = 28) displayed signals of association with STAT4 with p = 7.6×10−6 and OR 3.61 (95% CI 2.09–6.23) (Table?" (PMID 24386384, 2013). "In the case-only meta-analysis the STAT4 risk allele displayed signals of association with a poor renal outcome with severe renal insufficiency." (PMID 24386384, 2013). "In the case-only meta-analysis of the two cohorts, the STAT4 SNP rs7582694 was associated with severe renal insufficiency with p = 1.6×10−3 and OR 2.22." (PMID 24386384, 2013). "We also demonstrate for the first time in our case-only analysis, an association between STAT4 and a worse outcome in terms of severe renal insufficiency defined as a GRF <30 mL/min/1.73 m2 at follow up." (PMID 24386384, 2013). "An association between the STAT4 SNP rs7582694 and severe renal insufficiency at the genome wide significance level was also detected (Table?" (PMID 24386384, 2013). "In the case-only meta-analysis of the two cohorts there was a significant association between the STAT4 SNP rs7582694 and severe renal insufficiency with p = 1.6×10−3, OR 2.22 (95% CI 1.34–3.70) (Table?" (PMID 24386384, 2013). "Signals of association between STAT4 and the development of severe renal insufficiency were detected, with a p-value of 0.02, OR 1.91 (95% CI 1.11–3.28) for SNP rs11889341." (PMID 24386384, 2013). "There was 64% power to detect an association between the STAT4 risk allele rs11889341 and severe renal insufficiency." (PMID 24386384, 2013). "We could early on show that the STAT4 risk gene is associated with increased risk for stroke, nephritis, and renal failure." (PMID 41503065, 2025). "Furthermore an association between the STAT4 SNP rs7582694 and severe renal insufficiency was present in our case-only meta-analysis of two independent SLE cohorts." (PMID 24386384, 2013). "We therefore conclude that the two groups proliferative nephritis and severe renal insufficiency are not completely overlapping and that the case-only association between STAT4 and severe renal insufficiency cannot be explained by an association with proliferative nephritis." (PMID 24386384, 2013). "Consequently, risk-variants of STAT4, via several different effects in the immune system, could promote a progressive autoimmune process in the kidney, which ultimately may lead to renal failure." (PMID 24386384, 2013). "We had 62% power to detect an association between the STAT4 risk allele rs7582694 and severe renal insufficiency in our case-only analysis of cohort I. However, the addition of cohort II increased the strength of the association between STAT4 and severe renal insufficiency." (PMID 24386384, 2013). "This assumption is also supported by the strong connection between the STAT4 risk gene variant, enhanced CD8 T cell response and renal failure." (PMID 41503065, 2025). "Genetic variants in STAT4 have been proposed to associate with SLE and LN in general, and with a more severe subtype of LN and renal failure." (PMID 34127828, 2021). "In this analysis the association between the STAT4 SNP rs7582694 and severe renal insufficiency was no longer significant after correction for multiple analyses (p = 0.020, OR 1.91, 95% CI 1.11–3.30) (Table?" (PMID 24386384, 2013).
bladder cancer (5 papers, 2022 to 2024). "M. Li and colleagues discovered that in vitro experiments showed a significant upregulation of STAT4 expression in bladder cancer (BCa) cell lines compared to the human normal bladder epithelial cell line." (PMID 39597056, 2024). "Similar results have been reported in bladder cancer, where the expression of STAT4 in cancerous tissues was higher than that in adjacent non‐cancerous tissues at both the protein and mRNA level." (PMID 38107057, 2023).
colorectal cancer (5 papers, 2022 to 2025). A primary or metastatic malignant neoplasm that affects the colon or rectum. "High expression of STAT4 was found in colorectal cancer tissues, compared to adjacent tissues and silencing of STAT4 resulted in the weakening of colorectal cancer proliferation and invasion." (PMID 38107057, 2023). "Interestingly, the co‐transcription between STAT3 and STAT4 has been reported in colorectal carcinoma, but whether STAT4 indirectly transactivates CD274 (coding PD‐L1) through synergistic effect with STAT3 remains unknown." (PMID 38107057, 2023). "In addition, the Y chromosome gene KDM5D drives male-specific metastasis and worse outcomes in colorectal cancer harboring KRAS alterations, which activates STAT4 to increase KDM5D, repressing the expression of genes governing cell adhesion and immune recognition." (PMID 39751827, 2025).
Crohn disease (5 papers, 2010 to 2014). A gastrointestinal disorder characterized by chronic inflammation involving all layers of the intestinal wall, noncaseating granulomas affecting the intestinal wall and regional lymph nodes, and transmural fibrosis. "Analysis for gene-gene interaction of IL12B with IL23R and STAT4 variants, respectively, regarding susceptibility to Crohn's disease (CD)." (PMID 22479607, 2012).